PNPLA3 (patatin like domain 3, 1-acylglycerol-3-phosphate O-acyltransferase )
Diseases named in the same sentence as PNPLA3 in open-access papers (continued):
Sharing a sentence is not in itself a finding about the gene and the disease.
metabolic syndrome (64 papers, 2011 to 2025). A cluster of metabolic risk factors for CARDIOVASCULAR DISEASES and TYPE 2 DIABETES MELLITUS. "MASLD is the hepatic manifestation of metabolic syndrome (metS), driven by genetic variants like PNPLA3 rs738409 G and strongly associated with metabolic comorbidities, including obesity, T2DM, hyperlipidaemia and hypertension." (PMID 40893881, 2025). "Individuals with PNPLA3 NAFLD have minimal features of metabolic syndrome and are carriers of the common I148M variant in patatin-like phospholipase domain-containing protein 3 (PNPLA3) gene." (PMID 39878508, 2025). "When moving to longitudinal studies, in a cohort of 144 patients with metabolic syndrome and with a median follow‐up of 17 months, Mantovani and colleagues observed that the presence of the PNPLA3 G allele was independently associated with more rapid decline in kidney function by eGFR." (PMID 39412170, 2025). "Although there is an evident bidirectional link between NAFLD and metabolic syndrome (MS), disconnections between liver fat and insulin control have been reported specifically in PNPLA3 gene variants, which are characteristic of the Hispanic population here studied, with susceptibility to NAFLD." (PMID 36769628, 2023). "In Model 3, gender, PNPLA3 rs738409, dyslipidemia, weight gain ≥10 kg after age 20 and ALT elevation were the independent predictors in patients with normal weight." (PMID 26485523, 2015). "In Model 2, gender, PNPLA3 rs738409, hypertension, dyslipidemia and weight gain ≥10 kg after age 20 were the independent predictors in the patients with normal weight." (PMID 26485523, 2015). "Individuals with metabolic NAFLD have multiple features of metabolic syndrome and are not carriers of the common I148M variant in patatin-like phospholipase domain-containing protein 3 (PNPLA3) gene." (PMID 39878508, 2025). "Additionally, visceral obesity, T2DM, dyslipidemia, and arterial hypertension are well-established risk factors promoting MASLD onset and progression, with genetic predispositions, such as PNPLA3 and TM6SF2 polymorphisms, further increasing susceptibility." (PMID 40219006, 2025). "We explore transcriptional regulation of PNPLA3 in the context of metabolic syndrome and T2D." (PMID 40630828, 2024). "Lean Asian NAFLD patients without metabolic syndrome are more likely to carry the PNPLA3 rs738409 GG allele, which can account for the similar prevalence of NAFLD between Asians and Caucasians." (PMID 36618688, 2022). "Data have shown that Metabolic Syndrome, rather than the gene polymorphisms studied (PNPLA3 rs738409, TM6SF2 rs58542926 and MBOAT7 rs641738), predicted an increased mortality owing to either overall causes or cardiovascular diseases among NAFLD subjects." (PMID 33572544, 2021). "An important finding of our research was the lack of statistically significant associations between the PNPLA3 genotypes and the components of metabolic syndrome." (PMID 34833467, 2021). "The PNPLA3 rs738409 variant does not modify the disease through changes in insulin sensitivity, metabolic syndrome, body mass index, or dyslipidemia." (PMID 31877771, 2019). "Of note, polymorphisms in PNPLA3 and TM6SF might be “master regulators” of metabolic syndrome outcomes, which potentially determine the full range of NAFLD manifestations from hepatic fat accumulation to liver cancer." (PMID 28594920, 2017). "This indicates that components of the metabolic syndrome might be intermediate variables on the pathway from PNPLA3 rs738409 and TM6SF2 rs58542926 to health services utilization." (PMID 26847197, 2016). "At baseline, the PNPLA3 C/G genotype carriers tended to have hypertension or dyslipidemia compared to the G/G genotype carriers, and therefore these risk factors may be associated with the high prevalence of NAFLD." (PMID 26200108, 2015).
metabolic syndrome (continued). "In the whole series of subjects without CHC, low adiponectin levels (lower than 6 μg/ml, median value in controls) were associated with the presence of NAFLD, age, male gender, BMI, dyslipidemia, ALT, insulin levels, PNPLA3 I148M alleles (p = 0.01), and ADIPOQ genotype (p = 0.009)." (PMID 22898488, 2012). "On the other hand, patients without the PNPLA3 polymorphism had more signs of metabolic syndrome." (PMID 40244110, 2025). "However, the disease associated genetic variants of PNPLA3 are not linked with risk factors such as insulin sensitivity or body mass index (BMI) and do not affect related metabolic syndromes such as dyslipidemia or type 2 diabetes." (PMID 27757845, 2017). "On the other hand, it may affect patients without the metabolic syndrome phenotype, but with genetic predisposition, where liver steatosis is due to genetic impairment of lipolysis, such as in the presence of genetic variation of PNPLA3 gene." (PMID 40244110, 2025). "We did not evaluate for any genetic polymorphisms for the presence of fatty liver such as Patatin-like phospholipase domain-containing protein 3 (PNPLA3) in our study; and found that 163 (42.4%) of patients with NAFLD didn’t have metabolic syndrome." (PMID 31057993, 2019). "Emerging genetic evidence supports this notion in MASLD, showing that variants like PNPLA3 and TM6SF2, while strongly associated with hepatic fat and fibrosis, do not independently increase CVD risk in the absence of metabolic syndrome." (PMID 41567808, 2025). "Variants increasing liver PDFF, such as those in PNPLA3 and TM6SF2, impair hepatic lipid export, promoting fat accumulation without systemic dyslipidemia." (PMID 40922984, 2025). "A clinical cohort study of the relationships of DAA treatment with PNPLA3 rs738409 and TM6SF2 rs58542926-induced dyslipidemia as well as the improvement of renal function in patients with non-genotype 3 chronic HCV infection is currently in progress (to be published later)." (PMID 37400794, 2023). "In our study, the prevalence of metabolic syndrome did not present differences regarding the PNPLA3 genotypes, which indicated that the management of metabolic factors was important regardless of genotype." (PMID 34833467, 2021). "We can consider the PNPLA3 genotype to be an important predictor of the degree of hepatic fat loading, even in subjects without metabolic syndrome." (PMID 34833467, 2021). "It has also been shown by others that the GCKR variant associates with dyslipidemia, while this is not the case for many other NAFLD risk-increasing genotypes such as PNPLA3 and that it increases the risk of NAFLD in obese individuals." (PMID 32841307, 2020). "Unfortunately, due to the retrospective nature of this current analysis, the subjects were not genotyped and their PNPLA3 and TM6SF2 and other SNPs associated with the metabolic syndrome were not available." (PMID 36419503, 2020). "The G allele in PNPLA3 rs738409 increases the risk of NAFLD in the general population, especially in subjects without metabolic syndrome." (PMID 26042596, 2015). "PNPLA3 does not affect the components of metabolic syndrome." (PMID 34833467, 2021). "On the other hand, individuals with genetic variants in the Patatin-like phospholipase domain containing 3 (PNPLA3), responsible for hydrolysis of triacylglycerol molecules in adipocytes, are susceptible to NAFLD development regardless of the existence of metabolic syndrome." (PMID 33680375, 2020). "These patients do not suffer from the metabolic syndrome, nor are they obese, but they do often carry specific genetic polymorphisms that have been associated with an increased propensity for developing NAFLD and NASH, such as PNPLA3 rs738409." (PMID 31877771, 2019).
metabolic syndrome (continued). "Variants such as PNPLA3 and TM6SF2 have been associated with hepatic fat accumulation independent of metabolic syndrome, while lifestyle and environmental exposures—including diet composition, physical inactivity, and gut microbiome dysbiosis—may further influence disease expression." (PMID 41437157, 2025). "Furthermore, considering the importance of PNPLA3 polymorphisms in the etiology of NAFLD and, more crucially, HCC, genetic testing of particular groups, such as individuals with NAFLD but no metabolic syndrome symptoms, may be prudent." (PMID 36320966, 2022). "In other words, our data support the view that “Not all forms of MASLD were created equal” and that metabolic syndrome-related MASLD has a greater impact on the aortic stiffening and early carotid atherosclerosis as compared to the PNPLA3-related form." (PMID 40244110, 2025).
type 2 diabetes (36 papers, 2012 to 2026). "Next, the risk of type 2 diabetes was examined and the PNPLA3 148M allele was also associated with a significantly higher risk of type 2 diabetes at baseline after adjusting for age, gender, and BMI (O.R. 1.09, 95% C.I. 1.01-1.39, P = 0.040)." (PMID 22724004, 2012). "These large studies will also scrutinise the sequential use of biomarkers and explore the potential added value of genotyping individuals for common genetic risk variants of MASLD, such as PNPLA3 I148M, as was recently suggested for individuals with type 2 diabetes and an indeterminate FIB-4 result." (PMID 38334817, 2024). "Moreover, the PNPLA3 148M allele was associated with a marginally increased risk of developing type 2 diabetes in the overall study (O.R. 1.04, 95% C.I. 0.98-1.11, P = 0.104)." (PMID 22724004, 2012). "Several studies have identified PNPLA3 as being associated with testosterone and SHBG levels, and it has also been linked to type 2 diabetes." (PMID 40892850, 2025). "In two different studies performed in elderly patients (mean age around 70 years) with type 2 diabetes, Mantovani and colleagues found lower eGFR and higher prevalence of CKD in those carrying the PNPLA3 rs738409 polymorphism, independently from NAFLD." (PMID 35327522, 2022). "cT1-increasing alleles at 4 variants (in SLC30A10, SLC39A8, TM6SF2, and PNPLA3) were associated with higher ALT and AST (all with p values <2×10−5) and higher risk of type 2 diabetes (all with p <0.002, except the SLC30A10 variant)." (PMID 32247823, 2020). "While the overall increased risk of the PNPLA3 148M allele for type 2 diabetes in the Go-DARTS study was only 4%, in the severely obese a 37% increased risk per 148M allele for type 2 diabetes was found." (PMID 22724004, 2012). "For example, neither rs738409 C>G in PNPLA3 nor rs58542926 C>T near TM6SF2 (risk alleles for type 2 diabetes) were significantly associated with differences in fasting insulin, glucose or HbA1c." (PMID 32720691, 2020). "This implies that NAFLD is heterogeneous and that “Obese/Metabolic NAFLD” but not NAFLD due to the PNPLA3 or TM6SF2 genetic variants predisposes to type 2 diabetes and cardiovascular disease." (PMID 27128911, 2016). "Two studied variants (rs738409C>G in PNPLA3 and rs58542926 near TM6SF2) are positively associated with type 2 diabetes through large GWAS yet we found them not to be associated with fasting insulin or glucose." (PMID 32720691, 2020).
non-alcoholic steatohepatitis (32 papers, 2011 to 2025). "Beyond its influence on steatosis, the PNPLA3 I148M variant is also linked to more severe liver disease progression, including nonalcoholic steatohepatitis (NASH), fibrosis, and hepatocellular carcinoma." (PMID 41303369, 2025). "Increased total energy intake and the PNPLA3 risk genotype GG have been associated with non-alcoholic steatohepatitis (NASH)." (PMID 38257154, 2024). "Conversely, changes in genetic variation were more prominent in lean NAFLD, such as the GG variant in the patatin‐like phospholipase domain containing 3 (PNPLA3) was independently associated with nonalcoholic steatohepatitis and fibrosis." (PMID 36163589, 2022). "More than fifty studies demonstrating that the PNPLA3 rs738409 G allele is a risk factor for non-alcoholic steatohepatitis (NASH), liver cirrhosis in NASH or alcoholic liver disease have been published in the past decade." (PMID 31527889, 2019). "A single nucleotide polymorphism (SNP) of the PNPLA3-gene is associated with development of non-alcoholic steatohepatitis and a worse outcome in alcoholic liver disease." (PMID 26599080, 2015). "As previously reported in detail, there is an association between the PNPLA3 I148M variant with alcoholic or non-alcoholic steatohepatitis." (PMID 23505555, 2013). "In the context of non-alcoholic steatohepatitis the PNPLA3 risk allele promotes hepatic lipid accumulation and severity of fibrosis." (PMID 22087248, 2011). "The downregulation of Patatin-like phospholipase domain-containing protein 3 (Pnpla3) in KO mice is consistent with human research, where genetic variants of PNPLA3 have been linked to non-alcoholic steatohepatitis (NASH) and NAFLD, and higher liver TAG content." (PMID 38167156, 2024). "Patatin-like phospholipase domain-containing 3 (PNPLA3) rs738409 polymorphism (I148M) is strongly associated with non-alcoholic steatohepatitis and advanced fibrosis; however, the underlying mechanisms remain largely unknown." (PMID 37298640, 2023). "PNPLA3, TM6SF2, and MBOAT7-TMC4 have been reported to be associated with elevated ALT levels and the histologic parameters of nonalcoholic steatohepatitis and severity of fibrosis." (PMID 36110512, 2022). "On the one hand, the rs738409 G-allele encoding the I148M variant of patatin-like phospholipase domain-containing protein 3 (PNPLA3) has been linked with non-alcoholic fatty liver disease (NAFLD) and non-alcoholic steatohepatitis in the general population." (PMID 33804385, 2021). "Regarding non-alcoholic steatohepatitis, a DNA microarray study in human liver revealed an upregulation of PNPLA3 in NASH vs. healthy controls." (PMID 27128907, 2016). "In the United States (U.S.), Hispanics have the highest prevalence of MASLD and metabolic dysfunction-associated steatohepatitis (MASH), driven in part by a higher population frequency of the PNPLA3 I148M variant, while African Americans have lower rates compared to White people/persons/person." (PMID 41585799, 2025). "Common genetic variation in the patatin-like phospholipase domain containing 3 (PNPLA3) and transmembrane 6 superfamily member 2 (TM6SF2) genes have been associated with an increased risk of developing NAFLD, nonalcoholic steatohepatitis (NASH), and fibrosis in adults." (PMID 38496563, 2024). "We conducted a meta-analysis to assess the association between patatin-like phospholipase domain-containing 3 (PNPLA3) rs738409 polymorphism and nonalcoholic fatty liver disease (NAFLD) and its subtypes simple steatosis(SS) and nonalcoholic steatohepatitis (NASH)." (PMID 25791171, 2015). "We used real-time polymerase chain reaction (PCR) analysis to analyze the hepatic expression of PNPLA3 and lipid metabolism-related genes in 55 morbidly obese subjects with normal liver histology (NL, n = 18), simple steatosis (SS, n = 20), and non-alcoholic steatohepatitis (NASH, n = 17)." (PMID 27128907, 2016).
alcoholic liver diseases (25 papers, 2011 to 2025). A disorder caused by damage to the liver parenchyma due to alcohol consumption. "We aimed to analyze the association between the PNPLA3 genotype and augmented inflammatory response in transplant candidates with end-stage alcoholic liver disease (ALD)." (PMID 40731922, 2025). "A study showed that PNPLA3 rs738409 polymorphism was closely related to alcoholic liver disease in Chinese Han men." (PMID 37424875, 2023). "The PNPLA3 rs738409 variant has now been associated with HS in cases of chronic liver diseases with different etiologies, including alcoholic liver disease, CHC, and non-alcoholic fatty liver disease." (PMID 28797039, 2017). "Subsequent investigations analysed PNPLA3 variant p.I148M (rs738409) in alcoholic Mestizo individuals and demonstrated an overrepresentation of the GG-genotype in those with alcoholic liver disease." (PMID 22276112, 2012). "Here, we performed a cross-sectional analysis to study the potential role of the PNPLA3 p.I148M variant in liver cancer associated with alcoholic liver disease as compared to patients with HCV-induced HCC." (PMID 22087248, 2011). "This idea is further emphasized by our multivariate regression model, which confirmed PNPLA3 148M homozygosity as independent risk factors for HCC among our patients with alcoholic liver disease." (PMID 22087248, 2011). "Finally, patients with PNPLA3 (rs 738409) polymorphism have been linked to HCC in patients with alcoholic liver disease." (PMID 35008267, 2021). "Finally, genetic associations between HCC development and alcoholic liver disease have been identified: patients with PNPLA3 (rs 738409) polymorphism have been linked to HCC in patients with alcoholic liver disease." (PMID 35008267, 2021). "In particular, the I148M variant of the patatin-like phospholipase domain-containing protein-3 (PNPLA3) gene has been strongly associated with NAFLD, ALT concentration, and alcoholic liver disease." (PMID 32841307, 2020). "PNPLA3 rs738409 2 risk alleles has been identified a risk factor for developing HCC associated with NAFLD, alcoholic liver disease or chronic HCV infection.The role of central obesity as a risk for HCC is also emerging as shown in a large European study." (PMID 26950933, 2016). "While our genetic assays were not specifically designed to differentiate between metabolic and alcohol-related liver disease, emerging evidence suggests that certain variants—particularly PNPLA3 rs738409 and MBOAT7 rs641738—are enriched in both MASLD and alcoholic liver disease." (PMID 40650184, 2025). "A recent meta-analysis of individual participant data revealed that the genetic association between a missense variant of PNPLA3 (rs738409) and HCC risk was more pronounced in patients with alcoholic liver disease in comparison with patients with chronic HCV infection." (PMID 28968953, 2017).
Hypertension (25 papers, 2014 to 2026). The presence of chronic increased pressure in the systemic arterial system. "Patients with and without PNPLA3 I148M variant had similar characteristics, with the exception for arterial hypertension, which was less prevalent in patients with I148M variant." (PMID 29150621, 2017). "For Model 1, multivariate regression analysis identified arterial hypertension (OR = 2.59, 95p = 0.016), decreased HDL (OR = 3.12, p = 0.019), and the PNPLA3 rs738409 GC/GG genotype (OR = 2.39, p = 0.019) as significant independent predictors of MASLD." (PMID 40864759, 2025). "We performed multivariate analysis using sex, age, hypertension, T2DM, hyperlipidemia, PNPLA3 genotype, the FIB-4 index at baseline, and FIB-4 index at 1 year as factors." (PMID 33086582, 2020). "While PNPLA3 status did not independently predict ferritin levels, carriers had a significantly higher prevalence of hypertension (50.0% vs. 25.0%, p = 0.038) and a non-significant trend toward low HDL-C (65.0% vs. 42.9%, p = 0.070)." (PMID 41977232, 2026).